MFAP4 (microfibril associated protein 4)
Diseases named in the same sentence as MFAP4 in open-access papers (continued):
Sharing a sentence is not in itself a finding about the gene and the disease.
atherosclerosis (4 papers, 2013 to 2025). A disease characterized by the build-up of fatty material and calcium deposition in the arterial wall resulting in partial or complete occlusion of the arterial lumen. "MFAP4 is closely associated with various remodeling-related diseases, such as atherosclerosis and arterial injury-induced remodeling." (PMID 40406620, 2025). "Particularly, Ang II infusion also results in development of atherosclerosis, and the importance of MFAP4 in atherosclerosis-independent AAA model remains to be investigated." (PMID 34805319, 2021). "MFAP4 is a component of the vascular ECM, and the data suggest that serum MFAP4 reflects the severity of the degree of atherosclerosis/calcification meaning that MFAP4 synthesis from VSMCs might be suppressed when both the intima and medial layer is calcified." (PMID 24349233, 2013). "Although further investigation of the distribution and function of MFAP4 in atherosclerosis as well as its relation to the ECM are warranted, this may be addressed in future studies." (PMID 24349233, 2013). "This may be due to the release of MFAP4 from VSMCs in the medial layer into the circulation, or the increased elastase activity in atherosclerosis, which reduces elastin content in atherosclerotic vessels, leading to decreased MFAP4 synthesis bound to elastin in the ECM." (PMID 40406620, 2025).
atrial fibrillation (4 papers, 2022 to 2025). A disorder characterized by an electrocardiographic finding of a supraventricular arrhythmia characterized by the replacement of consistent P waves by rapid oscillations or fibrillatory waves that vary in size, shape and timing and are accompanied by an irregular ventricular response. "In the heart, MFAP4 was upregulated in a model of angiotensin II (Ang II)-induced atrial fibrillation, while MFAP4-deficient mice showed reduced atrial enlargement and fibrosis." (PMID 35805199, 2022). "Furthermore, the relevant MFAP4 pQTL is also an eQTL in left atrial tissue, and plasma MFAP4 levels have previously been associated with atrial fibrillation and degree of atrial fibrosis." (PMID 38225249, 2024).
cardiac hypertrophy (4 papers, 2023 to 2025). "Recently, animal studies have reported that MFAP4 deficiency inhibited myocardial hypertrophy and myocardial fibrosis, and improved cardiac function." (PMID 36650606, 2023). "On the other hand, MFAP4 is considered protective in stress-induced cardiac hypertrophy." (PMID 40406620, 2025). "On one hand, MFAP4 deficiency reverses aortic constriction and isoproterenol-induced cardiac dysfunction without affecting cardiac hypertrophy in these models." (PMID 40406620, 2025). "Besides large arteries and arterioles, MFAP4 mRNA transcript levels were relatively higher in myocardial tissue and lung, which is in agreement with its important role in cardiac hypertrophy, asthma and chronic obstructive pulmonary disease." (PMID 36650606, 2023).
hepatitis C (4 papers, 2016 to 2023). "MFAP4 levels were measured using an AlphaLISA immunoassay in a retrospective study including n = 542 hepatitis C patients." (PMID 27378383, 2016).
lung adenocarcinoma (4 papers, 2022 to 2026). A carcinoma that arises from the lung and is characterized by the presence of malignant glandular epithelial cells. "Accordingly, decreased MFAP4 expression in lung adenocarcinoma was confirmed in a separate study, where MFAP4 overexpression attenuated cell invasion and stemness in vitro and inhibited tumor growth in vivo." (PMID 35805199, 2022). "In lung adenocarcinoma, MFAP4 expression is highly downregulated; moreover, micro-RNA147b was identified to inhibit MFAP4 expression while promoting tumor cell proliferation, migration and colony formation." (PMID 35805199, 2022). "In lung adenocarcinoma, has-miR-147b promotes cells malignant aggressiveness by targeting MFAP4." (PMID 36357869, 2022). "Further studies revealed that upregulation of FOXF1/MFAP4 promoted anti-tumor immune responses through augmented dendritic cell and CD4+ T cell infiltration, facilitating crosstalk between lung adenocarcinoma and immune cells, and induction of multiple anti-tumor immune pathways." (PMID 41596347, 2026). "This suggested that LINC02126 may play important roles in the development of lung adenocarcinoma by regulating the expression of DCN, COX7A1, PLAC9, LUM and MFAP4." (PMID 36357869, 2022).
Marfan syndrome (4 papers, 2020 to 2024). A disorder of the connective tissue. "MFAP4 is an extracellular protein that has been associated with elastic fibre formation and several diseases with defects in elastic fibres, including Marfan syndrome and chronic obstructive pulmonary disease." (PMID 38740766, 2024). "Further evidence about the role of MFAP4 in elastic tissues comes from studies on Marfan syndrome (MFS), a rare genetic disorder of the connective tissue caused by mutations in the fibrillin-1 gene." (PMID 35805199, 2022). "Altered MFAP4 glycosylation could potentially affect binding to elastogenic proteins, including fibrillin-1 or LTBP4 isoforms, possibly affecting formation and maintenance of microfibrils and elastic fibres, which are compromised in Marfan syndrome." (PMID 38740766, 2024).
melanoma (4 papers, 2020 to 2025). A malignant, usually aggressive tumor composed of atypical, neoplastic melanocytes. "To further evaluate the activity of human MFAP4 promoter, we transfected the plasmids into mouse fibroblasts (NIH/3T3 cells), human melanoma cells (MeWo cells), and mouse melanoma cells (B16-F10 cells)." (PMID 33182307, 2020).
aneurysm (3 papers, 2019 to 2023). Bulging or ballooning in an area of an artery secondary to arterial wall weakening. "In addition, MFAP4 is associated with aneurysms and peripheral arterial diseases." (PMID 37063972, 2023). "We selected and validated the genes randomly (Lrrc17, Gxylt2, Mfsd2a, Scube and Ank2) and based on their role in aneurysms (Mmp12, Spp1, Ctss) or cardiovascular complications (Mfap4, Igfbp2) or inflammatory signalling pathways (Ccls and Ccrs)." (PMID 30677223, 2019). "Our glycoproteomics analysis revealed that MFAP4 glycosylation is enhanced, as well as its expression during the advanced, aneurysmal stages of MFS compared with control aneurysms from patients without MFS." (PMID 31315432, 2019).
asthma (3 papers, 2019 to 2022). "MFAP4-deficient mice were partially protected from all major hallmarks of experimental asthma development—airway hyperresponsiveness, inflammation and pulmonary remodeling." (PMID 35805199, 2022). "Moreover, MFAP4 deficiency limited peribronchial fibrosis and reduced total lung collagen content induced by experimental asthma." (PMID 35805199, 2022). "The objectives of this study were to investigate if the serum level of MFAP4 (sMFAP4) is associated with (a) asthma and (b) allergic sensitization in adolescents and young adults, and (c) whether sMFAP4 at the time of asthma diagnosis is associated with persistent asthma." (PMID 31251481, 2019). "Among the top flow central nodes, several genes, such as SLC39A8, SOX17, and MFAP4 show a direct relationship with asthma and COPD." (PMID 32041952, 2020). "It has been proposed that MFAP4 promotes the development of asthma in vivo and proasthmatic pathways of bronchial smooth muscle cells in vitro." (PMID 31251481, 2019). "More specifically, it has been found in literature that the expression levels of SLC39A8, SOX17, and MFAP4 might directly affect both asthma and COPD." (PMID 32041952, 2020). "The nature of the present study does not allow us to conclude on the underlying cellular mechanisms nor to establish any causal relationship between MFAP4 and asthma." (PMID 31251481, 2019). "The result supports the hypothesis that MFAP4 plays a role in the pathogenesis of asthma although the marker did not demonstrate any obvious potential as an asthma biomarker in adolescents and young adults with asthma." (PMID 31251481, 2019).
bladder cancer (3 papers, 2011 to 2025). "In prostate and urinary bladder cancer, MFAP4 acts as a tumor suppressor, and by targeting MFAP4, miR-147b increased aggressiveness in LUAD cells." (PMID 39170516, 2024).
emphysema (3 papers, 2022 to 2026). "Essentially, studies with Mfap4 knockouts revealed a significant decrease in alveolar surface area by 25%, and mice developed emphysema-like changes at the age of 6 months." (PMID 37932771, 2023).
endometriosis (3 papers, 2022 to 2025). The growth of functional endometrial tissue in anatomic sites outside the uterine body. "Recently, MFAP4 was identified as both an endometriosis-related and an RM-related hub gene in immune cells, further supporting the conclusions of this study." (PMID 39508749, 2025). "MFAP4 was found to be positively correlated with CD8+ T cells in a study of endometriosis." (PMID 39822989, 2025). "Q RT-PCR was used to detect the expression of ACKR1, LMNB1, MFAP4, NMU, and SEMA3C mRNA in ectopic endometrial tissues of patients with endometriosis." (PMID 36277723, 2022). "ACKR1, LMNB1, MFAP4, NMU, and SEMA3C were upregulated in ectopic endometrial tissues of patients with endometriosis compared with normal endometrium (P < 0.001), which was consistent with the results of bioinformatics analysis." (PMID 36277723, 2022).
heart failure (3 papers, 2023 to 2025). Inability of the heart to pump blood at an adequate rate to meet tissue metabolic requirements. "The results showed that, compared to normal samples, HMGN2, HTRA1, LTBP2, and MFAP4 were significantly upregulated in heart failure, while MYH6 was downregulated (p < 0.001)." (PMID 40406620, 2025). "External dataset validation and analyses indicate that MFAP4 is highly expressed in myocardial tissues of heart failure patients, consistent with previous studies, while RT-qPCR results show low expression of MFAP4 in the plasma of HF patients." (PMID 40406620, 2025). "This is the case of FMOD, whose expression is upregulated in clinical and experimental heart failure or MFAP4, a protein whose abrogation in mice worsens cardiac function upon chronic pressure overload." (PMID 37565451, 2023). "However, only SDSL showed an AUC value greater than 0.7 in the test set, whereas EGFL7, SMTNL2, MFAP4, TAGLN, SGPP2 and SMTNL2 showed AUC values greater than 0.5, so SDSL may be a high risk factor in patients with heart failure." (PMID 38250028, 2023). "The analysis revealed that heart failure samples had significantly higher expression levels of EGFL7, SDSL, PPP1R13l, SMTNL2, MFAP4, and TAGLN genes, which may promote the development of heart failure." (PMID 38250028, 2023).
idiopathic pulmonary fibrosis (3 papers, 2016 to 2025). Idiopathic pulmonary fibrosis (IPF) is a nonneoplastic pulmonary disease that is characterized by the formation of scar tissue within the lungs in the absence of any known cause. "Interestingly, MFAP4 was described as a potential biomarker for liver and lung fibrosis before." (PMID 37935709, 2023). "However, recent data suggests that MFAP4 is not elevated in sera of patients with idiopathic pulmonary fibrosis (IPF)." (PMID 27378383, 2016).
liver cirrhosis (3 papers, 2013 to 2025). "MFAP4 has been suggested to be actively involved in the pathogenesis of several matrix remodelling-associated diseases, such as liver cirrhosis, cardiovascular disorders, and cancer, through its interactions with integrins and proinflammatory signalling, as well as modulating the TGF-β pathway." (PMID 40243889, 2025). "MFAP4 is further found in a soluble form and serum MFAP4 (sMFAP4) levels are recognized to vary with cardiovascular disease and pulmonary disease although the strongest association is found with high sMFAP4 and liver cirrhosis." (PMID 29884190, 2018).
ovarian carcinoma (3 papers, 2017 to 2023). A malignant neoplasm originating from the surface ovarian epithelium. "Furthermore, our results focused on methylation status of CAMs and revealed a 3-gene (CTNNA1, DLC1, MFAP4) methylation signature with a prognostic significance that may provide a new biomarker for personalized treatment in ovarian cancer." (PMID 28881822, 2017).
renal fibrosis (3 papers, 2016 to 2024). A final common manifestation of a wide variety of chronic kidney diseases characterized by glomerulosclerosis and tubulointerstitial fibrosis. "MFAP4 is involved in unilateral ureteral obstruction-induced renal fibrosis through the regulation of the NF-κB and TGF-β/Smad pathways." (PMID 38898508, 2024). "MFAP4 was also shown to promote renal fibrosis in the unilateral ureteral obstruction mouse model, where it was reported that the renal TGF-β pathway, plasminogen activator inhibitor-1, collagen I and fibronectin were all downregulated in MFAP4-deficient mice." (PMID 35805199, 2022). "The list of genes includes Fblim1, Epha2, Wisp1, Parvg, Madcam1, Mybpc2, Cdh3, Gpr56, Troap, Pstpip1, Pcdh8, Nlgn2 and Mfap4, genes that based on Pubmed and Kidney and Urinary Pathway Knowledge Base12 searches have not been previously associated with renal fibrosis." (PMID 27189340, 2016).
Ureteral obstruction (3 papers, 2022 to 2025). Obstruction of the flow of urine through the ureter. "In the absence of MFAP4, downregulation of pro-inflammatory cytokines (IL-1β and TNF-α) and concurrent inhibition of NF-κB signaling pathway activation can mitigate the inflammatory response induced by unilateral ureteral obstruction." (PMID 39508749, 2025).
Ventricular arrhythmia (3 papers, 2023 to 2024). "MFAP4 deficiency mitigates myocardial fibrosis and ventricular arrhythmias induced by aortic constriction or isoproterenol in mice but does not significantly affect the hypertrophy response." (PMID 37869159, 2023). "Mechanistically, Mfap4 deletion could attenuate cardiac fibrosis and ventricular arrhythmias, suggesting its potential as a therapeutic target in HF prevention." (PMID 38397416, 2024).
allergic asthma (2 papers, 2019). A asthma with a basis in a pathological type I hypersensitivity reaction. "Our main result supports previous in vitro and in vivo studies investigating the possible role of MFAP4 in allergic asthma." (PMID 31251481, 2019).
gastric cancer (2 papers, 2022 to 2025). A primary or metastatic malignant neoplasm involving the stomach. "It has previously been reported that MFAP4 is a cancer-promoting gene with a positive effect on the development of gastric cancer." (PMID 35488236, 2022). "In addition, MFAP4 was significantly differentially expressed in a variety of other cancers including colorectal and gastric cancers." (PMID 40061958, 2025).
glioma (2 papers, 2022 to 2025). A benign or malignant brain and spinal cord tumor that arises from glial cells (astrocytes, oligodendrocytes, ependymal cells). "Association between MFAP4 mRNA expression and the clinical parameters of glioma patients from The Cancer Genome Atlas (TCGA)." (PMID 40061958, 2025). "Significant associations between MFAP4 levels, immune infiltration, ferroptosis, and immune checkpoint genes were found in glioma tissues." (PMID 40061958, 2025). "The main objective of this study is to comprehensively investigate the functions and mechanisms of MFAP4 associated with immunotherapy resistance in glioma." (PMID 40061958, 2025). "Thus, our findings suggest that elevated MFAP4 levels are closely associated with mechanisms that promote immune escape in glioma tumor cells, thereby promoting tumor growth and progression." (PMID 40061958, 2025). "Analysis of the ROC curve for MFAP4 showed an area under the ROC curve (AUC) of 0.833, indicating that MFAP4 was able to accurately differentiate between tumor and normal control samples, and that its expression in gliomas has a high diagnostic value." (PMID 40061958, 2025). "Gene expression profiles of all types of tumor samples showed that MFAP4 expression was significantly elevated in high-grade gliomas, especially in GBM, and furthermore, MFAP4 expression increased with WHO grade." (PMID 40061958, 2025). "To explore the possible function of MFAP4 in gliomas, we further explored the genes found to be co-expressed with MFAP4 in TCGA using LinkedOmics." (PMID 40061958, 2025). "OS analysis of the TCGA dataset showed that MFAP4 was negatively correlated with the prognosis of glioma." (PMID 40061958, 2025). "Future studies should combine in vitro and in vivo experiments to elucidate the mechanism of action of MFAP4’s biological functions in glioma cells." (PMID 40061958, 2025). "Overall, our study provides the first evidence that MFAP4 is aberrantly overexpressed in gliomas and correlates with adverse clinicopathologic features." (PMID 40061958, 2025). "To achieve this goal, we will identify the specific functions of MFAP4 in glioma immunotherapy through multiple approaches." (PMID 40061958, 2025). "In the context of gliomas, few previous studies have focused on the role of MFAP4 despite its expression in many human cancers." (PMID 40061958, 2025). "Our goal is to thoroughly elucidate the role of MFAP4 in immunotherapy resistance in glioma and provide substantial support for the development of more effective immunotherapeutic approaches." (PMID 40061958, 2025). "Links across MFAP4 levels and Glioma clinicopathological characteristics, shown through logistic regression assessment." (PMID 40061958, 2025). "We also performed functional and pathway enrichment analyses of MFAP4 in gliomas to explore its biological functions and potential molecular mechanisms in gliomas." (PMID 40061958, 2025). "This showed a significant correlation between MFAP4 and the 3,974 genes co-expressed in gliomas (FDR<0.05, P < 0.05)." (PMID 40061958, 2025). "Our study demonstrated that MFAP4 is aberrantly overexpressed in gliomas and correlates with adverse clinicopathological features." (PMID 40061958, 2025). "MFAP4 levels were correlated with glioma stage, histological type, and 1p/19q status, and independently predicted overall survival (OS), disease-specific survival (DSS) and progression-free interval (PFI)." (PMID 40061958, 2025). "Specifically, our analyses will focus on the expression levels of MFAP4 in gliomas and its correlation with tumor immunotherapy responses." (PMID 40061958, 2025). "To address this gap, we analyzed transcriptomic data from different databases such as TCGA, GTEx and GEO to explore the potential impact of MFAP4 in gliomas." (PMID 40061958, 2025). "Detailed exploration of the functions and mechanisms of MFAP4 in gliomas is essential for gaining new insights and developing therapeutic strategies." (PMID 40061958, 2025).